IL10 (interleukin 10)
Diseases named in the same sentence as IL10 in open-access papers (continued):
Sharing a sentence is not in itself a finding about the gene and the disease.
glioma (continued). "Glioma cells secrete factors such as IL-10, IL-4, IL-6, M-CSF, TGF-β, and prostaglandin E2 that suppress the immune functions of microglia when these cells are located inside the tumor." (PMID 26149494, 2015). "Mice implanted with gliomas expressing both IL-10 and IL-2 had significantly smaller (99% smaller) tumor sizes and increased T-cell infiltration at 14 days post-implantation compared to mice with IL-10−/IL-2− tumors." (PMID 26217588, 2015). "IL10 was an important cytokine during glioma progression as a result that it promoted glioma invasion as well as an immunosuppressive environment." (PMID 25978454, 2015). "High grade gliomas expressed higher level of IL10 produced by glioma infiltrating macrophages (GIMs)." (PMID 25978454, 2015). "Ex vivo, IL-10 both increases glioma proliferation and confers invasive potential to glioma cells in a dose-dependent manner." (PMID 26217588, 2015). "TGF-β and IL-10, both of which are produced by gliomas in vivo, have been shown to induce Treg conversion in vitro." (PMID 26217588, 2015). "IL-10 increases glioma cell proliferation in vitro and its expression has been found to be correlated with the extent of malignancy in gliomas." (PMID 24675569, 2014). "STAT3 activation in glioma TAMs is induced by many mediators known to compose the local tumor microenvironment such as IL-10, IL-6, EGF, and FGF." (PMID 23737783, 2013). "In one report, cyclooxygenase-2 (COX-2) overexpressing glioma via Prostaglandin E2 (PGE2) synthesis induced mature DCs to express high levels of IL-10, which in turn induced CD4+ T cells that secreted copious amounts of IL-10 and TGF-β." (PMID 23874336, 2013). "Among the immunosuppressive mediators upregulated in glioma TAMs, those that appear to exert a predominate effect include cytokines IL-10, TGF-β, and cell surface antigens B7-H1, and FasL." (PMID 23737783, 2013). "In contrast cytokines IFN-α, TNF-α,IL-12p70, IL-1β, IL-6, IL-8 and IL-10, as well as metalloproteinases -2 and -9 were present in equalamounts in glioma C6 and astrocyte CMs." (PMID 23637756, 2013). "Consistent with this notion, IL-10-producing CD4+ cells have been demonstrated to effect tumor rejection in a murine glioma model by augmenting CTL and NK cell response." (PMID 23874336, 2013). "Both cell types in glioma exhibit M2 phenotype polarization, such as upregulation of CD163 and CD204, as well as via secretion of M2-associated cytokine including IL-4, IL-10, and TGF-β." (PMID 24202450, 2013). "The expression levels of IL-10 in glioma tissue correlate with glioma grade as well as a degree of brain invasiveness." (PMID 24202450, 2013). "Microglial cells recruited by glioma can promote tumor growth, dictated by paracrine loops responsible for glioma initiation and progression (e.g., IL-6, IL-10, TGF-β, prostaglandins, G-CSF, and GM-CSF, and growth factors such as EGF, VEGF, HGF, and SCF)." (PMID 22319429, 2012). "Serum IL10 levels are elevated in patients with high-grade glioma, and IL10 enhances glioma cell growth and migration in vitro." (PMID 22312408, 2012). "In the present study, we demonstrate that microglia and macrophages accumulate in GL261 experimental gliomas, adapt an anti-inflammatory “M2” phenotype, express arginase-1, IL-10 and MMPs." (PMID 21901144, 2011). "Monocytes express a wide range of PRPs including TLRs, NLRs, RLRs and CLRs which in glioma TME enable immunosuppression (through IL-10 and TGF-β cytokine release), fuel inflammation (through the secretion of IL-1β and IL-18) and preserve tumor growth (through VEGF, MMPs, and IL-1β expression)." (PMID 41157253, 2025). "A major immunosuppressive cytokine in the glioma TME is IL-10." (PMID 41157253, 2025). "Higher IL-10 and TGF-β levels are associated with worse outcomes in glioma." (PMID 40136652, 2025).
glioma (continued). "From a mechanistic perspective, in the context of glioma, memory B cells may contribute to tumor growth by promoting an immunosuppressive microenvironment through the secretion of cytokines such as IL-10, which can inhibit anti-tumor T cell responses 49,50." (PMID 40657381, 2025). "IL10 is reported to support immune evasion in CD133+ stem-like glioma cells." (PMID 38322416, 2024). "TMZ-resistant glioma secretes interleukin-10 (IL-10) and transforming growth factor-β (TGF-β), recruiting regulatory T cell (Treg) and inhibiting the activity of T cells and natural killer cell (NK cell), subsequently forming an immunosuppressive microenvironment." (PMID 38443927, 2024). "Moreover, the normal functioning of DCs can be affected by TGFβ and IL-10 cytokines, released by glioma cells." (PMID 39452154, 2024). "Enriched MAPKAPK2 expression in microglia/macrophages and glioma cells might facilitate the production of IL10 to promote glioma progression." (PMID 38322416, 2024). "As reported, IL10 secreted by glioma cells are thought to activate tumor-infiltrating immune cells such as microglia and macrophages, which would produce more IL-10 to compose the majority in glioma tissue." (PMID 38322416, 2024). "In glioma or ovarian cancer models, Stat3 was phosphorylated both in cancer cells and macrophages by direct co-culture and promoted cancer cell proliferation and production of IL-6 or IL-10 from the macrophages." (PMID 37296952, 2023). "Gliomas with reduced anti-glioma immune responses expressed interleukin-10 (IL-10) and TGF-β." (PMID 36770950, 2023). "In the cancer-immunity cycle, we found genes that inhibit the cycle, including the glioma-secreted and cell-surface immunosuppressive factors, TGFB1, VEGFA, ARG1, IL10, and CD70, they were highly expressed in the high-risk group and were positively correlated with the risk score." (PMID 37891828, 2023). "A recent study revealed interactivity between GAMs and astrocytes, which stimulated the JAK/STAT pathway in astrocytes to express various anti-inflammatory cytokines, including TGF-β, IL-10, and G-CSF, contributing to the migration and proliferation of gliomas." (PMID 36969175, 2023). "The lack of adequate activation of T lymphocytes in the tumor microenvironment may be because anti-tumor responses of T lymphocytes are inhibited by soluble factors such as TGF-β and IL-10 that are secreted by glioma cells." (PMID 37274252, 2023). "Glioma cell-produced PGE2 can promote DC-producing IL-10, inhibiting effector T-cell responses." (PMID 37781367, 2023). "Furthermore, in vivo data demonstrated that lncRNA HOXA-AS2 silencing suppressed Treg cell proliferation, which resulted in reduced secretion of TGF-β and IL-10 in spleen and finally reduced immune tolerance in glioma." (PMID 35181676, 2022). "FAT1 expression was also observed to correlate positively with the expression of surrogate markers of MDSCs [programmed death ligand-1 (PD-L1), PD-L2, and interleukin (IL)-10] in glioma tumors, suggesting a potential role of FAT1 in MDSC-mediated immunosuppression." (PMID 35720420, 2022). "The regulatory T (Treg) cells accumulating in the TIME of glioma could inhibit immune surveillance and attack by excreting IL-10, IL-35 and TGF-β, which possibly predicts the poor prognosis of patients with gliomas." (PMID 36358495, 2022). "The study showed that IL-10 increased cell growth and invasion into glioma cells." (PMID 36009467, 2022). "Meanwhile, IL10 significantly enhances glioma cell growth and invasion." (PMID 36505882, 2022). "In vitro, it has been demonstrated that IL-10 upregulates KPNA2 (a gene coding for nuclear import of proteins); at the same time, knockdown experiments showed that glioma cell growth and invasion were significantly reduced, suggesting IL-10 as a potential target for glioma patients’ treatment." (PMID 33804731, 2021).
glioma (continued). "Moreover, IL-6+IL-10+ NKTs exhibit a weak ability to induce apoptosis in glioma cells but have an immunosuppressive effect on CD8 T cell activity." (PMID 34603399, 2021). "Single-cell transcriptomics uncovered a gene signature in glioma composed by immune effector molecules and inhibitory feedback mechanisms (genes such as Ifn-γ, Ctla-4, Pdcd1, IL-10, Tgf-β1 or Ido1) that lead to the reprogramming of T cells subsets that become unable to target the cancer cells." (PMID 34540682, 2021). "In addition, stress-induced phosphoprotein 1 (STIP1) secreted by TAMs induces proliferation of glioma cells in vitro, while IL-10 was shown to promote glioma cell proliferation via JAK2/STAT3 signaling in a glioma model." (PMID 34503065, 2021). "Classic immunosuppressive cytokines associated with glioma are TGF-β and IL-10." (PMID 32542437, 2021). "Furthermore, the supernatant from glioma stem cells (GSCs) inhibits the phagocytic activity of TAMs and induces IL-10 and TGF-β secretion." (PMID 34603399, 2021). "IL-10 also promotes expression of the negative checkpoint molecule PD-L1 on glioma-associated macrophages and peripheral monocytes." (PMID 31973059, 2020). "Furthermore, the production of IL-10 and expression of IL-10 receptor in monocytes was upregulated by culture them in glioma-conditioned medium, and PD-L1 expression was increased in monocytes treated with IL-10." (PMID 31781673, 2019). "A study of gliomas showed that monocytes cultivated in glioma-conditioned medium expressed increased levels of PD-L1, which could be mitigated by IL-10 inhibition or IL-10 receptor inhibition." (PMID 31781673, 2019). "In vitro study found that EM-1 could elicit rapid activation of ERK1/2 in rat C6 glioma cells, and morphine induced a decrease of IL-10 and an increase of IL-12 secretion via p38 MAPK pathway in monocyte-derived human dendritic cells." (PMID 30442166, 2018). "In addition, the tumor microenvironment contains very high levels of tumor-secreted immunosuppressive cytokines, such as IL-10, which contribute to impaired lymphocyte responses in patients with glioma." (PMID 28641579, 2017). "In PBMCs culture, glioma-derived exosomes directly promoted IL-10 and arginase-1 production and downregulation of HLA-DR by unstimulated CD14+ monocytic cells, that displayed an immunophenotype resembling that of monocytic myeloid-derived suppressor cells (Mo-MDSCs)." (PMID 28107450, 2017). "In experimental gliomas, tumor infiltrating microglia and macrophages upregulate their anti-inflammatory molecular signatures; notably arginase 1 (Arg1), transforming growth factor β, matrix metalloprotease 2, and interleukin 10 (IL-10)." (PMID 29164051, 2017). "Finally, to confirm the role mediated by IL-10 from M2 macrophage in the promoting of glioma cells, we've blocked the IL-10 using neutralizing mono-antibody against IL-10 both in vivo and in vitro." (PMID 27765933, 2016). "Moreover, considering the pivotal role of IL-10 in the promotion of proliferation of glioma cells, we've meanwhile evaluated IL-10 expression in glioma tissues." (PMID 27765933, 2016). "Further analysis showed that IL-10 expression can also be used as an independent prognostic factor for patients with glioma, suggesting that blocking of IL-10 could be an alternative therapeutic strategy for patients with glioma." (PMID 27765933, 2016). "Furthermore, we for the first time found that IL-10 stimulated the JAK2/STAT3 pathway in glioma cell lines U271 and U87 through interaction with JAK2 in a protein-protein interaction fashions." (PMID 27765933, 2016). "Further, IL-10 was found to be able to interact with JAK2 in glioma cells." (PMID 27765933, 2016). "Based on the evidence we obtained, we've reasoned that IL-10 may play a major role in the promoting of proliferation of glioma cells." (PMID 27765933, 2016).
glioma (continued). "Unlike gliomas, however, where the vast majority of IL-10 is produced by tumor-associated macrophages and microglia, several peripheral tumors produce IL-10 directly." (PMID 26217588, 2015). "Human gliomas have long been known to produce IL-10 in vivo." (PMID 26217588, 2015). "Rather than secreting IL-10 directly, however, glioma cells produce soluble factors that induce tumor-associated macrophages (TAMs) and microglia to secrete the majority of the cytokine." (PMID 26217588, 2015). "In conjunction with other cytokines, IL-10 can also facilitate anti-glioma immune responses." (PMID 26217588, 2015). "It has been postulated that the complex interplay between IL-10 and IFN-γ might regulate the immunosuppressive effect of indolamine 2,3-dioxygenase (IDO) tryptophan metabolism by glioma-associated APCs, resulting in a stronger anti-tumor immune response." (PMID 26217588, 2015). "At the same time, other peripheral tumors, similar to gliomas, may also rely upon TAMs to produce the majority of IL-10." (PMID 26217588, 2015). "For example glioma cells produce cytokines, such as IL-10, IL-4, IL-6, TGFβ and prostaglandins E2." (PMID 24689533, 2014). "Activated microglia can also release inflammatory products, such as nitrites, IL-10 and urea, that may exert detrimental effects on glioma cells." (PMID 24689533, 2014). "In fact RAPA and RAD significantly increased iNOS expression and activity, while on the same time significantly reducing IL-10 gene expression induced by C-CM, thus suggesting that the drugs prevent the acquisition of a M2 phenotype in response to glioma factors promoting a classic M1 activation." (PMID 25051975, 2014). "At variance, microglia exposed to basal glioma-derived factors, i.e. a condition resembling the early stage of pathology, shows a more specific pattern of activation, with increased M2b polarization status and up-regulation of IL-10 only." (PMID 24689533, 2014). "An analog of thalidomide, CC-5103 increases the secretion of critical cytokines of the tumor microenvironment, including IL-2, IFN-γ, TNF-α, and IL-10, and is currently being evaluated in clinical trials for the treatment of recurrent or refractory pediatric central nervous system tumors." (PMID 23717811, 2013). "Notably, glioma cells are known to induce immune suppression via the production of interleukin-10 (IL-10) and TGF-β." (PMID 22323550, 2012). "The cytotoxicity of glioma-associated microglia/macrophages and their ability to induce effective anti-tumor T-cell responses are impaired, most likely due to the glioma-secreted immunosuppressive factors like TGF-β, IL-10, and prostaglandin E2." (PMID 24213237, 2012). "Our findings suggest that GM-CSF and IL-10 could be important cytokines for establishment of a pro-invasive phenotype of glioma-infiltrating microglia/macrophages." (PMID 21901144, 2011). "Exposure of DCs to cyclo-oxygenaase-2 overexpressing gliomas results in IL-10 production by DCs which also drives Tr1 response, which may be dependent on robust secretion of Prostaglandin E2 from the glioma." (PMID 21711933, 2011). "In the periphery, consistent with other tumor models that include glioma models, the proportion of Tregs in the spleen increased substantially relatively early in tumor development, which was accompanied by increased frequencies of IL-10-expressing Tregs." (PMID 19226468, 2009). "Thus, the strong production of PGE2 in glioma cells exposed to NaF may contribute to the concomitant increase in IL-10 (reinforcing a feedback loop that suppresses inflammation)." (PMID 40497976, 2025). "To evaluate the combined impact of the developing glioma and SorLA loss from host cells on the tumor microenvironment, we first assayed the levels of selected cytokines (TNFα, MIP2, CCL5, CXCL1, IL1β, IL2, IL6, and IL10) in the tissue lysates derived from tumor-bearing and tumor-free hemispheres." (PMID 38499808, 2024).
glioma (continued). "In addition, patients with glioma experience elevated levels of an inhibitory cytokine, IL-10, which inhibits the expression of pro-inflammatory factors, mediates the function of Tregs, and inhibits the CD8+ T-cell-mediated cytotoxicity and antigen presentation of antigen-presenting cells." (PMID 36928507, 2023). "Furthermore, TGFβ and IL-10 secreted by glioma cells can disrupt the normal function of DCs." (PMID 37705736, 2023). "Moreover, under the influence of glioma cells, GAMs become a major source of molecules (e.g., interleukin-1 beta (IL-1β), interleukin-10 (IL-10), vascular endothelial growth factor (VEGF)) that support tumor growth and contribute to an immunosuppressive tumor microenvironment." (PMID 37368789, 2023). "Interestingly, glioma stem cells induce IL-10 secretion by microglia, suggesting the presence of a bidirectional signaling axis in which glioma stem cells induce IL-10 secretion by microglia, which can then lead to aberrant synapse formation, an avenue of future research." (PMID 33187183, 2020). "Finally, although we conducted subgroup analyses for IL‐6, IL‐8, IL‐10, and TNF‐α with glioma risk to explore the potential sources of heterogeneity, high heterogeneity still existed in the studies of IL‐4, IL‐12, IL‐17, IL‐23, TGF‐β, and MCP‐1 based on the limited number of included studies." (PMID 31599129, 2019). "However, we found no direct correlation of IL-8 or IL-10 with risk of developing VTE in our cohort of patients with glioma." (PMID 31847343, 2019). "Thus, coordinated regulation between PD-L1 and IL-10 may result in reduced glioma-derived antigen presentation and hamper the effective antitumor response even further." (PMID 30619286, 2018). "IL-10 may serve as a vital cytokine upregulating PD-L1 expression in circulating monocytes and tumor-infiltrative macrophages in an autocrine/paracrine pattern in gliomas." (PMID 30687086, 2018). "Furthermore, glioma cells and GAMs express Tgf-β and Il-10, which may contribute to inhibition of T cell activation and proliferation, and stimulate differentiation of naïve T cells into Treg25." (PMID 29242629, 2017). "Moreover, blockage of the IL-10 secreted from M2 macrophage could be an alternative potential therapeutic strategy in light of the recalcitrance of glioma to the current standard therapeutic strategy." (PMID 27765933, 2016). "Firstly, IL-10 was just shown to be significantly higher in our setting among the interleukins secreted from M2 macrophage, which doesn't mean IL-10 is the only one effective cytokine that played a major role in the mediation of malignant behavior of glioma cells." (PMID 27765933, 2016). "Furthermore, IL-10 has been shown to confer growth advantages to glioma tissues." (PMID 26217588, 2015). "But in glioma tissues, there is obviously predominant expression of Th2 type cytokines, it may result tumor cells escape from immune response, so the abnormal secretion of IL-4, IL-10 and IL-13 may play an important role in the occurring and developing of human glioma." (PMID 23663500, 2013). "M2-polarized GAMs secrete IL-10 and TGF-β, while low levels of IL-12, creating an immunosuppressive effects in the TME and also promoting the proliferation of glioma stem cells (GSCs)." (PMID 40661781, 2025). "For example, glioma cells secrete immunosuppressive cytokines such as TGF-β and IL-10, which inhibit immune activation and suppress the expression of MHC class II molecules on monocytes." (PMID 41268299, 2025). "In glioma patients, cancer cell-derived PGE2 enhances IL-10 secretion by DCs, which subsequently promotes Treg activity." (PMID 40136652, 2025). "The secretion of IL-6, facilitated by hypoxic glioma-derived exosomes, has an additive effect on increasing CD163 and IL-10 expression via the same STAT3 pathway, thereby enhancing tumor progression." (PMID 40361384, 2025).